IL5 (interleukin 5)
Diseases named in the same sentence as IL5 in open-access papers (continued):
Sharing a sentence is not in itself a finding about the gene and the disease.
tumor (continued). "TH2 cells secrete IL4, IL5, IL10, IL13, and IL17 - all of which have been shown to contribute to the tumor-promoting role of this subtype, even though IL4, IL5, and IL13 have been shown to contribute to the growth and metastasis of cancer." (PMID 41019045, 2025). "As MF progresses, there is a decline in anti-tumor Th1 responses (e.g., IFN-γ, IL-12) and a predominance of Th2 cytokines such as IL-4, IL-5, and IL-13." (PMID 40864740, 2025). "CD4 + Th cells modulate the tumor microenvironment by secreting cytokines such as IFN-γ, TGF-β, IL-4, IL-5, and IL-6." (PMID 40441260, 2025). "Future research should explore cytokine-blocking therapies (e.g., anti-IL-5 monoclonal antibodies) to disrupt the paracrine pathways driving both HES and tumor growth." (PMID 41398896, 2025). "Under the control of IL-5 axis, eosinophils can express CCL22 that supports the recruitment of Tregs facilitating the colonization of lung metastasis in different tumor models." (PMID 40050933, 2025). "Eosinophils seem to react differently to various mediators, including IFN-γ, IL-5, IL-33, CCL1124,43–46, and tumor-derived TSLP47, resulting in either enhanced cancer cell killing or promotion of tumor growth." (PMID 38951159, 2024). "The 16-biomarker panels were divided into three categories of inflammatory markers (SAA, CRP, NLR, PLR, and LDH), TH1/TH2 cytokines (IL-2, IL-4, IL-5, IL-6, IL-8, IL-10, IFNγ, TNF, and GM-CSF), and HCC tumor markers (AFP and PIVKA-II)." (PMID 38409200, 2024). "While this to the best of our knowledge is the first study to identify the relationship between AREG and IL-5 in the context of tumor immunology, it is known that AREG is expressed by human eosinophils in response to IL-5 exposure." (PMID 38831884, 2024). "Pro-tumour cytokines such as vascular-endothelial growth factor α (VEGF-α) and the interleukins (IL) IL-4, IL-5, IL-6, IL-10, and IL-13 produced by T-helper (Th2) lymphocytes have also been linked to the pathogenesis of MCD." (PMID 40729293, 2024). "Both SIA‐CIgG CAR‐T cells and HER2 CAR‐T cells secreted more IL‐2, IL‐5, TNF‐α, IFN‐γ, and IL‐13 compared to non‐transduced T cells when eliminating tumor cells." (PMID 39178136, 2024). "High Il33 expression in tumor cells recruits and activates TH2 and ILC2 cells which secrete pro-tumorigenic cytokines such as Il4, Il5, and Il13." (PMID 38942797, 2024). "For example, studies have suggested that tumor-promoting Th2 cells have high levels of IL-10 and TGF-β, whereas Th2 cells with high expression of IL-3, IL-5, IL-13, and GM-CSF exhibit pro-inflammatory and anti-tumor immunity." (PMID 37332039, 2023). "Thus, type II cytokines, particularly IL-5 may play an important role in anti-tumor immunity." (PMID 36376448, 2023). "This combined treatment notably elevated CD4+ T-cell presence within the tumor microenvironment and increased IL-5 and IL-13 tumor levels, while simultaneously decreasing CD38 in the tumor stroma." (PMID 37689790, 2023). "In the context of cancer, the type 2 cytokines IL-4, IL-5, IL-9, and IL-13 along with ILC2s, Th2, and Th9 cells may either promote or inhibit tumorigenesis in a context-dependent manner that involves complex interactions with cancer cells and the constituents of the tumour microenvironment." (PMID 37455828, 2023). "NK cells participate in autoimmunity by secreting IL-1, IL-5, IL-8, IL-10, tumor necrosis factor-α (TNF-α), and Interferon-γ (IFN-γ) to kill aging, virus-infected, and tumor cells." (PMID 36428567, 2022). "Second, the group of cytokines were triggered in response to the resection procedure and then sustained in the newly regrown tumor (IL4, IL5, IL10, IL17, CCL2, IFN-γ and GM-CSF)." (PMID 35884700, 2022). "On the contrary, they also release various cytokines, such as INF-γ, after being activated by tumor antigens, preventing macrophages from migrating away from the tumor antigens, as well as TNF-ɑ, IL-4, and IL-5." (PMID 36611336, 2022).
tumor (continued). "T lymphocytes mediate tumor immunity by secreting various cytokines into the TME, such as IL-2, IL-4, IL-5, IL17, IL-21, IL-22, and IFN-γ." (PMID 35464411, 2022). "Th2 is one of the special subtypes of CD4+ helper T cell (Th cell) that mainly secretes cytokines such as IL-4, IL-5, and IL-10, and excessive Th2 cells could affect the tumour-suppressive immune microenvironment, seriously reducing the anti-tumour effect, leading to the malignant growth of tumours." (PMID 35591854, 2022). "RagKO.ATAμκ Tg mice lack mature T cells, including NKT/NKT2 cells, but still have IL-5-producing ILC2s, and these mice showed earlier and strongly increased ATA B cell tumor generation." (PMID 36050343, 2022). "The CD4+ Th cells modulate tumor microenvironment by secreting cytokines such as IFN-γ, TGF-β, IL-4, IL-5, and IL-6." (PMID 33995619, 2021). "Compared with pretherapeutic levels, IL-5 and IFN-γ levels largely increased as the tumor progresses (P < 0.01)." (PMID 34239620, 2021). "TH2 cells are responsible for the increase in population of tumor infiltrating M2 macrophages and eosinophils in the TME, via their expression of IL-5 and IL-13, which regulate TGF-β secretion and immunosuppressive responses." (PMID 34012451, 2021). "Tumor cells may secrete factors to promote Th2 and TAM2 (Tumor-Associated Macrophage) polarization, which in turn amplify this type of inflammation via IL-4, IL-5 and IL-13, suppress anti-tumor Th1 polarization and responses, and correlate with MDSC infiltrates." (PMID 33498483, 2021). "While baseline IFNg is higher in the recurrent tumor, the level of TNFa, RANTES (CCL5), IP-10, IL-5, IL-10, MIP1a (CCL3), MIP1b (CCL4), and GM-CSF are all significantly lower in the recurrent tumor." (PMID 34221953, 2021). "Moreover, tumor cells or lymphocytes from TME may produce IL-5, GM-CSF, or IL-4." (PMID 34572273, 2021). "IL‐5 secretion in tumor microenvironment leads to activation of CCR3 (CC motif chemokine receptor type 3)‐expressing eosinophils in blood and spleen of tumor‐bearing mice." (PMID 34128588, 2021). "Eosinophils are activated by IL33, IFN-γ, and IL-5, and activated eosinophils secrete MBP, tumor necrosis factor (TNF)-α, eosinophil peroxidase, and granzyme B, which facilitate the killing of tumor cells." (PMID 35011007, 2021). "In our study, we used a 3-color Fluorospot assay allowing analyses of tumor-specific IFN-y, IL-5 and IL-10 producing lymphocytes." (PMID 33006650, 2021). "In our study, we for the first time found that serum IL-5 and IFN-γ levels can be useful biomarkers reflecting the changes in tumor areas." (PMID 34239620, 2021). "Tumor-infiltrating T, B, and NK cell levels and plasma concentrations of Th1 (IL-2, IFN-γ, and TNF-α), Th2 (IL-4, IL-5, IL-6, and IL-10), Th9 (IL-9), and Th17 (IL-17A, IL-17F, IL-21, and IL-22) cytokines were evaluated." (PMID 32802733, 2020). "Secondly, in the presence of interleukin (IL)‐2, IL‐5 and other cytokines, combination therapies enhance CD8 T‐cell activation and their ability to attack tumour cells." (PMID 33078904, 2020). "In response to several stimuli such as IL-5, IL-33, CCL11, IFNγ and TNFα, eosinophils secrete cytotoxic proteins (MBP, ECP, EDN and granzymes), which can induce apoptosis of tumor cells." (PMID 33233582, 2020). "To evaluate the involvement of adhesion molecules in the formation of cell conjugates among eosinophils and tumor cells, we carried out CLSM of IL-33 and IL-5 EO in co-culture with tumor cells." (PMID 31717819, 2019). "In the context of PDAC, IFN-γ–secreting Th1 cells were shown to slow tumor growth by stimulating the proliferation of CD8+ cytotoxic T cells, while IL-5–secreting Th2 cells promoted tumor growth by inhibiting CD8+ cells." (PMID 31112530, 2019). "Another IgE specific for the epithelial tumour antigen MUC-1 restricted cancer growth when expressed locally in tumours along with chemoattractant mediators MCP-1 and IL-5." (PMID 31544825, 2019).
tumor (continued). "Eosinophils remained elevated in the lungs after primary tumor resection, and to determine whether eosinophils influence 4T1 tumor growth in the lungs, we treated 4T1 tumor-bearing mice with an antibody against interleukin-5 (IL5) that has been shown to deplete eosinophils in murine model systems." (PMID 31488209, 2019). "Following tumor induction, administration of rIL-33 induced the development of IL-5-producing ILC2, which recruited and maintained eosinophils responsible for tumor cell death and tumor metastasis prevention." (PMID 30483263, 2018). "Briefly, IL-12, IL-17, GM-CSF, MIP-1α, IL-5, IFN-γ, IL-1Rα, IL-7, IP-10, IL-2R, IL-4,IL-15,MIP-1β levels were higher in the inflammation group and kept relative lower level in healthy and tumor groups." (PMID 28977824, 2017). "In contrast, some studies provide the finding that Th2-derived cytokines (IL-4, IL-5, IL-10, and IL13) show anti-tumor activities in vivo that are as strong as the anti-tumor activities of Th1 cytokines." (PMID 29299026, 2017). "We did, however, observe significant changes based on tumor status in inflammatory cytokines (IFN-γ, IL-6, IL-5, IL-2, IL-10) and a growth factor (FGF-basic)." (PMID 27893434, 2017). "In the present study, the Th2-class cytokines IL-10, IL-5 and IL4 were also decreased in response to the tumor challenge, but only in multiparous mice." (PMID 28966800, 2017). "Serum CCL2, IL-10, IL-5, IL-4, TNF-α, IL1-β and IL-12p70 levels increased with age irrespective of parity status, but were specifically reduced following OC tumor induction only in multiparous mice." (PMID 28966800, 2017). "Following tumor induction, administration of rIL-33 induced the development of IL-5-producing ILC2, which recruited and maintained eosinophils that induced tumor cell death and prevented tumor metastasis, possibly through an IL-4-dependent mechanism." (PMID 27882334, 2016). "Both B16F10 and LLC tumours exposed to Reovirus alone showed up-regulation of several favourable cytokines including Interferon-γ (IFN-γ) and IL-5 although the cytokines observed and the level of up-regulation varied between B16F10 and LLC." (PMID 27412241, 2016). "Our results show that endothelial and/or stromal cells within the tumour express higher levels of mouse-specific cytokines (MCSF, IFNG, IL5, IL7 and CXCL9) in VEGFA165 tumours compared with control tumours." (PMID 22045186, 2011). "During vaccination, the T cell immune response to autologous B-CLL tumor cells (as measured by the frequency of IFN-γ and IL-5 ELIspots) was markedly increased." (PMID 19922650, 2009). "IL-13, which is known to promoting the Th-2 phenotype in both malignant CTCL cells and non-malignant T cells, along with IL-5, plays a crucial role in tumor progression." (PMID 41221277, 2025). "Furthermore, the hyperactivation of miR-155 by STAT5 contributes to a TH2 phenotype, which, through its cytokines (IL-4, IL-5, and IL-13), inhibits the TH1 response, preventing an adequate defense of the organism against the tumor." (PMID 38435536, 2024). "Mechanistically, immunotherapy stimulates the production of IL-5 and IL-33 by CD4+ T cells, which induces the production of eosinophils in the bone marrow, increased systemic eosinophil circulation, and accumulation in the tumor site." (PMID 39496729, 2024). "Previous research also demonstrated that Th2 cells could secrete IL‐4 and IL‐5 contributing to antitumor response by regulating TME and recruiting other effector cells in the tumor model with vaccination." (PMID 37829505, 2023). "However, Th2 cells are considered to promote tumor progression due to the immunosuppressive substances they release, including TGF-β, IL-4, IL-5, and IL-13." (PMID 38203661, 2023). "Such tumor-mediated prolonged survival was reliant on tumor-secreted CCL11 but independent of IL-5 since anti-IL5-treated mice had eosinophils present in their colons." (PMID 37587450, 2023).
tumor (continued). "IL-5 itself had no direct effect on tumor proliferation but regulated the development of niches in metastatic sites that were conducive to tumor cell invasion through Tregs." (PMID 37587450, 2023). "IL-5 is known to promote eosinophil migration and function and although not well studied in tumor settings, eosinophils are thought to have cytotoxic effects on cancer cells." (PMID 36376448, 2023). "As evidenced by these results, GM-CSF imposes a negative effect on tumor growth and size, which is on par with that of IL-5, and also promotes eosinophils and T cells’ infiltration in the TME." (PMID 37587450, 2023). "The enhanced production of IL-5 and IL-13 was present in the splenic ILC2s of the tumor-challenged mice regardless of the disappearance of increased numbers of splenic ILC2s over time, which had been observed in tumor-free mice upon the tumor challenge." (PMID 37896962, 2023). "Eosinophil mediators, such as IL-5, IL-33, granulocyte–macrophage colony-stimulating factor (GM-CSF), thymic stromal lymphopoietin (TSLP), and CCL11 also determine eosinophil behavior toward tumor cells." (PMID 37587450, 2023). "Thus, we injected recombinant IL-5 into PK5L1940 and BRAF tumor-bearing mice at biologically relevant concentrations of the amount present in tumors receiving Th2 cells." (PMID 36376448, 2023). "The administration of recombinant GM-CSF and/or IL-5 in tumor-bearing mice significantly reduced tumor size, and no cytokine was more efficient than the other nor synergistic." (PMID 37587450, 2023). "By contrast, IL-5 production was not altered by this microenvironmental change in the lungs of 4T1/LM4 tumor-bearing mice." (PMID 35805039, 2022). "In both the tumor and spleen of the ApcMin/+ mice, IHS strongly suppressed the expression of IL-5 (p < 0.05), IL-6 (p < 0.05), IL-10 (p < 0.05), P-JAK1 (p < 0.05), P-JAK2 (p < 0.05), P-STAT3 (p < 0.05), and P-STAT5 (p < 0.05) and enhanced the P-STAT1 expression (p < 0.01)." (PMID 36014805, 2022). "Thus, we determined tumor soluble factors that include angiogenic (VEGF), type 1 response (TNF-α, IFN-γ), type 2 response (IL-4, IL-5), and regulatory (IL-10) soluble factors." (PMID 36233245, 2022). "Splenocytes from T. cruzi immunised non-tumour-bearing mice produced high levels of both IFN-γ and IL-5 when stimulated with T. cruzi-derived molecules, although a very low non-significant production of these cytokines was obtained when restimulated with an LL/2 protein lysate." (PMID 36499361, 2022). "Decreased infiltration of the tumor by CD4+ and CD8+ T cells and the increased presence of regulatory T cells as well as TH2 cytokines (IL [interleukin]-4, IL-5), transforming growth factor (TGF)-β, and IL-10, also lead to an immunosuppressive environment in the tumor." (PMID 36230474, 2022). "Following differentiation, TH2 cells secrete IL-4, IL-5, IL-10, IL-13, and IL-17, not all of which are beneficial in cancer and have been shown to contribute to the tumor promoting role of this subtype." (PMID 34012451, 2021). "Among these cytokines, we found that IL-5 expression by colon-derived ILC2s was most highly upregulated in tumour-bearing mice, whereas expression was not altered in the MLN or spleen compared to untreated mice." (PMID 33535624, 2021). "Sub-cutaneous injection of B16 melanoma cells into C57BL/6 wild type mice or in IL5-/- mice (with eosinophils depleted) leads to the same tumor growth, suggesting that eosinophils are not able to directly eliminate tumor cells." (PMID 34572273, 2021). "This microRNA was shown to indirectly regulate the expression of several cytokines (IL-5, IL-6, CCL-5, TNF-alpha) that in turn may alter the immune infiltration in the tumor microenvironment." (PMID 33544339, 2021).
tumor (continued). "Following short-term restimulation of colonic ILC subsets isolated from tumour-bearing CAC mice with phorbol myristate acetate and ionomycin we observed significant increases in TNF-α (ILC1), IL-5 and IL-13 (ILC2) and IL-17 (ILC3) production in tumour-bearing mice." (PMID 33535624, 2021). "Following differentiation, Th2 cells can produce IL-4, IL-5, IL-10, IL-13, and IL-17, not all of which are beneficial in cancer and contribute to tumor growth and metastasis." (PMID 35087869, 2021). "Altogether, ILC cells including NK cells could contribute to the increased level of TNF-alpha, GM-CSF, IFN-gamma, IL-4, IL-5, IL-13, IL-17, and IL-22, modulating TME and contributing to tumor progression or antitumor activities." (PMID 35008550, 2021). "Therefore, we determined tumor cytokine expression of type 1 (TNF-α and IFN-γ), type 2 (IL-4 and IL-5), and regulatory (IL-10) cytokines." (PMID 32547942, 2020). "In contrast, we did not observe polarization of CD11a/CD18 to the EO-tumor cell synapses in either IL-33-activated or control IL-5 EO." (PMID 31717819, 2019). "Specifically, a smaller tumor size was correlated with increases in CD45+CD11b+ cells present in the tumors (r = −0.956; p = 0.04), in serum MPO (r = −0.969; p = 0.03), in serum IL-5 (r = −0.948; p = 0.051), and in serum CXCL1 (r = −0.938; p = 0.06) concentrations." (PMID 31114758, 2019). "In contrast, IL-5 EO loosely adhered to tumor cells and exhibited electron-dense granules, indicating no or little degranulation." (PMID 31717819, 2019). "We found that depletion of eosinophils with anti-IL5 did not affect 4T1 metastatic growth in the lungs, indicating that 4T1 tumor cells can grow in the lungs independent from eosinophil levels." (PMID 31488209, 2019). "In addition, silencing PD-L1 or PD-L2 specifically on DCs enhanced proliferation of tumor-specific CTLs and CD4+ T-cells, augmented production of IFN-γ, tumor-necrosis factor alpha (TNFα), IL-2, IL-5, and IL-12 and promoted cytolysis of tumor cells in vitro." (PMID 30568653, 2018). "In this study, we noticed that anti-IL-25 treatment only reduced the IL-4-producing Th2 cells in the tumor microenvironment, but did not affect the expression of IL-5 and IL-13." (PMID 27909985, 2017). "Finally, based on tumor status, there were significant changes in proinflammatory cytokines (IFN-γ, IL-6, IL-5, IL-2, IL-10) and a growth factor (FGF-basic)." (PMID 27893434, 2017). "In our study, we observed a high level of proinflammatory cytokines, such as TNF-α, IFN-γ and IL-12 in sera from SZU-101-treated tumour-bearing mice, while no induction of TH-2 cytokines IL-4, IL-5 or IL-10 was detected." (PMID 25887995, 2015). "In relation to their ‘tunable’ function, mast cells in the local environment can also be detrimental for the tumours themselves, secreting immune mediators such as IL-1, IL-4, IL-5, IL-6 and TNF-α that can induce apoptosis of tumor cells and recruit inflammatory cells." (PMID 24212964, 2011). "According to our work, Th1 cytokines (IL-2 and IFN-γ) and Th2 cytokines (such as IL-4 and IL-5) are not the major cytokines produced by tumours." (PMID 17261184, 2007). "Importantly, IL-5 knockout mice had reduced survival and no eosinophil infiltration into the tumor challenge site, supporting the well-known role of IL-5 as an eosinophil differentiation and chemotactic factor." (PMID 36159781, 2022). "Previous studies showed that PD-1 blockade led to the augmentation of effector T cells in tumor sites, increasing the cytolytic activity of tumor-specific cells, increasing production of IL-2, INF-γ, TNF-α, IL-17, and IL-6, and decreasing the production of the Th2 cytokines such as IL-5 and IL-13." (PMID 35996120, 2022). "More importantly, tumour clearance was reduced in mice lacking the Th2 cytokines IL-4 and IL-5." (PMID 36261459, 2022).